TNF (tumor necrosis factor)
Diseases named in the same sentence as TNF in open-access papers (continued):
Sharing a sentence is not in itself a finding about the gene and the disease.
neuropathic pain (continued). "Their protective effects against neuropathic pain were mediated by inhibiting NOX-1, iNOS, by increasing the enzyme activity of catalase, and inhibition of inflammatory mediators, NF-κB, TNF-α, lipoxygenase, COX-2 enzymes, and PGE2." (PMID 33239680, 2020). "Minocycline has also indicated to reduce the cytokine levels (IL-1β, TNF-α, and IL-6), which promoted neuro-inflammation and decreased pain behavior in a CCI model of neuropathic pain." (PMID 27221523, 2016). "In several models of neuropathic pain, expression of TNF-α and TNFR1 is up-regulated in the spinal dorsal horn, and elevated levels of TNF-α induce spinal LTP in a JNK-, p38 MAPK-, and NF-κ B-dependent fashion." (PMID 24065916, 2013). "For example, spinal LXA4 and its aspirin-triggered form reduced TNF, IL-1β and IL-6 mRNA and protein levels in the DRG in a neuropathic pain model and in the spinal cord in a model of bone cancer-induced pain." (PMID 24086560, 2013). "In CCI neuropathic pain, chronic p.o. cryptotanshinone administration suppressed the increase in IL-1β, IL-6, TNF, PI3K/Akt signaling, determining an overall improvement in the paw withdrawal mechanical threshold and thermal withdrawal latency." (PMID 38398566, 2024). "Analyzing the genetic expression of proteins key to the TNF-α-necroptosis pathway in CCI and SNI neuropathic pain models, we detected the expression and cell localization of necroptosis-related proteins, including RIP1/p-RIP1, RIP3/p-RIP3, and MLKL/p-MLKL, in the ACC of SNI rats." (PMID 37895135, 2023). "In addition to inhibiting neuropathic pain behavior in SNL rats, quercetin inhibited inflammatory response by inhibiting pro-inflammatory cytokines TNF-α and IL-1β and reduced CCL-2 and MMPs, which play important roles in the pathogenesis of neuropathic pain." (PMID 32150953, 2020). "In nondiabetic injury neuropathic pain models, the inhibition of TNF-α also reduced neuropathic pain-related behavior." (PMID 24642694, 2014). "Microglial MAP kinases can be activated by IL-1β and TNF-α, inducing, via transcription factors such as NFκB, additional production of IL-1β, TNF-α, IL-6, IL-10, TGF-β, PGE2, BDNF, and cathepsin S and promoting the deleterious effects of microglial infiltration and phagocytosis in neuropathic pain." (PMID 24642655, 2014). "Indeed, TNF and BDNF are upregulated and released by DRG neurons and glia in inflammatory and neuropathic pain models and are strongly pro-nociceptive." (PMID 24642266, 2014). "Altogether, our study showed that TNF-α, via activating STAT3, mediated epigenetic upregulation of Nav1.6 in DRG and contributed to L5-VRT-induced mechanical allodynia, which provided a novel potential target for the treatment of nerve injury-induced neuropathic pain." (PMID 30736806, 2019). "Even though there are no studies on the efficacy of rubiscolin-6 for neuropathic pain, SNC-80, a representative DOR agonist, suppressed mechanical allodynia and injury-induced TNF-α upregulation in the sciatic nerve of a CCI rat model of neuropathic pain." (PMID 37373107, 2023).
Hypercholesterolemia (66 papers, 2006 to 2025). An increased concentration of cholesterol in the blood. "Despite persistent hypercholesterolemia, Maxadilan reduces lumen stenosis, apoptosis and TNF-α driven inflammation." (PMID 39769009, 2024). "An animal study in rats found that hypercholesterolemia decreased acetylcholine levels, increased acetylcholinesterase activity, and increased tumor necrosis factor (TNF) and amyloid-β42." (PMID 38802840, 2024). "Taken together, the results indicated that hypercholesterolemia-increased the accumulation of foam cells and the release of TNF-α and VEGF-A." (PMID 30125282, 2018). "The present study demonstrated that hypercholesterolemia increased the release of inflammatory cytokine TNF-α and then promoted intraplaque angiogenesis by enhancing VEGF-A/VEGFR-2 and FGF-2/FGFR-1 expression." (PMID 30125282, 2018). "Because TNFα is a central cytokine/adipokine in hypercholesterolemia, we next explored the functional consequences of the elevated levels of TNFα in patients with PH." (PMID 30583563, 2018). "Hypercholesterolemia, a medical disorder characterized by elevated levels of cholesterol in the bloodstream, has been found to potentially initiate an inflammatory response, resulting in an upregulation of pro-inflammatory cytokines such as TNF-α and IL-6." (PMID 38603728, 2024). "Similarly, some studies evaluating LDL apheresis performed in patients with familial hypercholesterolemia, have shown a decrease in TNF-α and soluble cell adhesion molecules and an increase in IL-10." (PMID 36614906, 2022). "Another experimental study convincingly associates high fat diet-induced hypercholesterolemia in aged ApoE-/- mice not only with elevated plasma levels of IL6, TNF-α, and interferon (IFN)-γ but also higher transcript levels of pro-inflammatory chemokine MCP-1 in brain tissue of these mice." (PMID 34349106, 2021). "Hypercholesterolemia, being overweight and oxidative stress can induce systemic and vital organ inflammation particularly the heart through overexpression of the pro-inflammatory cytokines which are TNF-α, IL-6, and IL-1 beta." (PMID 33827626, 2021). "Chronic inflammation has been reported to increase under hypercholesterolemic conditions and is the mechanism through which hypercholesterolemia induces tissue damage, resulting in the over-production of pro-inflammatory cytokines such as TNF-α, IL-1β, and IL-6 in the HFD-fed mice." (PMID 31920470, 2019). "In addition, several participants were taking medication: nine (9.4%) regularly took T4 (levothyroxine sodium), two (2.1%) antidepressants, one (1.0%) antihypertensives, one (1.0%) drugs for hypercholesterolemia, one (1.0%) an anti-TNFα drug, and one (1.0%) contraceptives." (PMID 36678250, 2023). "In addition to estrogenic-like activities, an anti-inflammatory effect of C. comosa extract has been reported in diet-induced hypercholesterolemia rabbit by decreasing production of several inflammatory cytokines, such as IL-1 and TNF-α, and of atherosclerotic plaque." (PMID 35588422, 2022). "CH reduces hypercholesterolemia-mediated atherosclerosis via modulating the inflammatory genes expression including TNF-α, toll-like receptors (TLR4), IL-17, and NLRP3 in the intestine and aorta compared with hypercholesterolemia control rats." (PMID 38966181, 2024). "The serum levels of IL-6, IL-8,IL-12, TNF-α and IFN-γ increased, while that of IL-4 and IL-10decreased in hypercholesterolemia." (PMID 39077184, 2022). "In this study, hypercholesterolemia increased NLRP3 and TNF-α, which is one of the most potent inducers of NF-κB." (PMID 33050202, 2020). "To examine the anti-neuroinflammatory effects of probucol plus cilostazol on focal cerebral ischemia with hypercholesterolemia, we assessed the mRNA levels of MCP-1, VCAM, iNOS, COX-2, TNF-α and IL-1β in the ischemic brain." (PMID 25017431, 2014). "It is shown to reduce glycemia, insulin index, hypercholesterolemia, oxidative stress, HbA1c, PAI-1, and tumor necrosis factor alpha." (PMID 23304216, 2012).
Hypercholesterolemia (continued). "Only a sub-population of medial SMC appears to express TNF-α and TNF receptors in response to hypercholesterolemia." (PMID 23675033, 2007). "However, in a situation when an increase in TNFα or its receptors might be secondary to hypercholesterolemia, one may expect a significant relationships between TNFα system and cholesterol rather in the obese group, presenting higher lipid levels and higher risk of accelerated atherogenesis." (PMID 16803616, 2006). "Cardio treatment significantly inhibited hypercholesterolemia, reduced levels of cardiac damage markers including LDH and CK, improved cardiac function, and reduced HFHC diet‐induced increased levels of inflammatory cytokines including TNF‐α and IL‐1β." (PMID 40951583, 2025). "The consumption of three types of margarine with different sterol contents did not influence TNF-α levels in non-obese participants with hypercholesterolemia." (PMID 40944222, 2025). "Therefore, induction of IL-1β, IL-6, and TNF-α by LDL(-) in macrophages has a link between LDL(-) and inflammation in hypercholesterolemia." (PMID 31534437, 2019). "The aim of the study was to assess the effect of 5α,6α-epoxycholesterol on experimentally induced hypercholesterolemia in rabbits, and the levels of homocysteine (HCY), asymmetric dimethylarginine (ADMA), paraoxonase-1 (PON-1), and inflammatory parameters (IL-6, TNF-α, CRP)." (PMID 29713239, 2018). "Others found that hypercholesterolemia increased the induction of plasma TNFα, or of aortic interleukin-1 and TNFα mRNA by gram negative endotoxins." (PMID 17997851, 2007). "Interestingly, a high fat diet in rats, or familial hypercholesterolemia in humans, did not increase TNFα production by isolated monocytes or whole blood treated with LPS in vitro." (PMID 17997851, 2007).
acute myeloid leukemia (65 papers, 1996 to 2025). Acute myeloid leukemia (AML) is a group of neoplasms arising from precursor cells committed to the myeloid cell-line differentiation. "Similarly, diosmin in acute myeloid leukemia treatment caused a decrease in tumor cell growth through caspase‐8 activation and increased TNF‐α expression and also downregulated the active proteins in the G0–G1 cell cycle phase, like Cdk2, Cdk4, and cyclin D1." (PMID 39554345, 2024). "Another study showed that oroxylin A markedly inhibited the cell proliferation and differentiation of acute myeloid leukemia (AML) cells generated by TNF-α." (PMID 39834817, 2024). "YTHDF2 acts as an oncogene that can facilitate cell proliferation and inhibit apoptosis via TNF signaling in acute myeloid leukemia." (PMID 37907575, 2023). "Furthermore, in vitro characterization of BMIF and PBP from adult acute myeloid leukemia (AML) patients showed differences in the potential to inhibit hematopoietic progenitor cell growth linked to different levels of TNFα and adiponectin." (PMID 36109804, 2022). "TNF-α is related to early hyperleukocytosis in acute myeloid leukemia (AML) and acute lymphoblastic leukemia (ALL)." (PMID 35547942, 2022). "In particular, compared to healthy children and adolescents, pediatric patients with acute myeloid leukemia showed higher concentrations of IL-6 and TNFα." (PMID 35335997, 2022). "Acute myeloid leukemia blasts have the ability to induce activation of the vascular endothelium through secretion of inflammatory cytokines, such as TNF-α and IL-1β." (PMID 33777944, 2021). "Other pathways can be linked to either the general function, response, or activation of phagocytic immune cells, or the presence of cancer cells, e.g., TNF alpha and NF-kappa B signaling, acute myeloid leukemia, and apoptosis." (PMID 34685549, 2021). "Supporting evidence from a clinical trial of a Smac mimetic, DEBIO1143, combined with daunorubicin and cytarabine in patients with acute myeloid leukemia (AML) revealed that the patients who responded more frequently showed an increase in plasma TNF-α levels." (PMID 31914150, 2020). "TNF-α treatment has been investigated as part of a combined therapy for acute myeloid leukemia due to its modifying effects on all-trans retinoic acid (ATRA) mediated differentiation into granulocytes." (PMID 31263060, 2019). "We previously reported that autocrine TNF-α (TNF) is responsible for JNK pathway activation in a subset of acute myeloid leukemia (AML) patient samples, providing a survival/proliferation signaling parallel to NF-κB in AML stem cells (LSCs)." (PMID 28039479, 2017). "It is known that the induction of HO-1 exerts a strong antioxidant and antiapoptotic effect as shown in acute myeloid leukemia resistance to TNFα and in the resistance of pancreatic tumors to gemcitabine." (PMID 26930712, 2016). "Similar findings in a mouse model of acute myeloid leukemia (AML) described a feedback loop between TNFα and NF-κB, confirmed by correlations in patient samples." (PMID 27058560, 2016). "In patients with cancer (acute myelogenous leukemia and myelodysplastic syndrome), fatigue severity was correlated with serum levels of the inflammatory cytokines interleukin (IL)-6, tumor necrosis factor (TNF)-α and the IL-1 receptor antagonist (IL-1RA)." (PMID 26435495, 2015). "IL-1, IL-6, and TNF were recently shown to promote deregulation of erythropoietin with resultant anemia in acute myelogenous leukemia (AML) and myelodysplastic syndromes (MDS)." (PMID 26538823, 2015). "In this study, we focused on the inhibitory effect of IL-32θ on TNF-α production in acute myeloid leukemia." (PMID 26516703, 2015). "For instance, in acute myeloid leukemia (AML), NF-kB dependent induction of HO-1 underlies resistance to TNF-α induced apoptosis." (PMID 22036896, 2011).
acute myeloid leukemia (continued). "Tumour necrosis factor (TNF)-alpha induces apoptosis in a human acute myeloid leukaemia cell line, Kasumi-1." (PMID 8562342, 1996). "Also, it induced apoptosis of acute myeloid leukemia cells by interaction with estrogen receptor‐β (ERβ) and triggered TNF‐α mediated extrinsic apoptotic pathway." (PMID 39554345, 2024). "KEGG pathways analysis of both clusters identified 13 overrepresented signaling pathways, including protein processing in the endoplasmic reticulum, TNF signaling pathway, estrogen signaling pathway, NF-κB signaling pathway and several cancer pathways (including acute myeloid leukemia)." (PMID 37848549, 2023). "In patients with acute myeloid leukemia, IL-32θ regulates the production of TNFα negatively." (PMID 35281066, 2022). "Notably, it has been reported that a positive feedback loop between NF-κB and TNFα promoted acute myeloid leukemia-initiating cell capability." (PMID 32641749, 2020). "In addition, these cells showed a higher concentration of IFN-γ, TNF-α and GM-CSF secretion and cytotoxicity to K562 cells and acute myeloid leukemia targets than resting NK cells." (PMID 31752805, 2019). "Their study also demonstrated that EriB could block TNF-induced NF-κB activation by inhibiting IκB degradation in acute myeloid leukemia cell." (PMID 30563578, 2018). "In this context, elevated IL-6 and TNFα levels have been correlated with adverse survival in patients with acute myeloid leukemia (AML)." (PMID 28947904, 2017). "The proinflammatory cytokine TNF-α is highly expressed in patients with acute myeloid leukemia (AML) and has been demonstrated to induce rapid proliferation of leukemic blasts." (PMID 26516703, 2015). "In acute myeloid leukemia, released HMGB1 promotes the proliferation of AML cells by influencing TNF-α production and interleukin 1β (IL - 1β) secretion, which promotes the release of stem cell factors." (PMID 40969278, 2025). "An intriguing observation from our study is the association of TNF-α polymorphisms with ALL rather than Acute Myeloid Leukemia (AML)." (PMID 39658797, 2024). "Tumor necrosis factor-alpha levels were substantially higher in T-acute lymphoblastic leukemia (T-ALL) cases, followed by acute myeloid leukemia (AML) and B-acute lymphoblastic leukemia (B-ALL), at the time of diagnosis, compared to the control." (PMID 35547942, 2022). "For instance, OA sensitized acute myeloid leukemia (AML) cells to TNF-α." (PMID 36139025, 2022). "Alteration of ILC subsets composition in patients with acute myeloid leukemia (AML), compared with the controls, could change the protective function of ILC1s by increasing their frequencies and reducing IFNγ and TNFα." (PMID 32117199, 2019). "The human acute myeloid leukemia cell line MUTZ-3 can be differentiated in vitro to dermal DC in the presence of GM-CSF, TNF-α and IL-4, and to LC in the presence of GM-CSF, TNF-α and TGF-β." (PMID 28713775, 2017). "The SPC839 is a dual inhibitor of AP-1 and NF-κB, showed good inhibitory activity against nitric oxide, TNF-α and FLT3, which is a potential target for acute myeloid leukemia (AML)." (PMID 37483616, 2023). "Interestingly NFκβ-inhibited acute myeloid leukaemia cells do not undergo TNF-induced apoptosis and hemeoxygense-1 (HO-1) is found to resist apoptosis." (PMID 32158360, 2020). "These NK cells are also shown to have increased TNF-α and IFN-γ production in response to primary acute myeloid leukemia (AML) blasts and control AML growth in mice." (PMID 28955340, 2017). "In acute myeloid leukemia (AML), there is a significant enrichment of ILC1s in peripheral blood compared to healthy controls and a significant reduction in the production of IFN-γ, TNF, and IL-5/IL-13 in total ILCs defined as Lin-IL7R+." (PMID 38567059, 2023). "Similarly, in patients with acute myeloid leukemia (AML), the PMA-induced TNF-α expression can be inhibited by IL-32θ." (PMID 29940981, 2018).